TLR8 (toll like receptor 8)
Diseases named in the same sentence as TLR8 in open-access papers (continued):
Sharing a sentence is not in itself a finding about the gene and the disease.
rosacea (4 papers, 2021 to 2024). A chronic erythematous skin disorder that affects the face. "Meanwhile, TLR8 mRNA in patients with rosacea bacterial chitin stimulation showed an increase in platelets, whereas other TLR mRNAs were not regulated, suggesting a role in platelet TLR8 responses to Candida." (PMID 36674552, 2023). "Therefore, we wonder if TLR7 or TLR8 expressed by specific skin cells are involved in the pathogenesis of rosacea." (PMID 37780385, 2023). "However, the role of TLR8 in the pathogenesis of rosacea and acne requires further exploration." (PMID 38321132, 2024). "Besides TLR2, our RNA‐sequencing data also showed that other TLRs (e.g., TLR4, TLR7, and TLR8) were also significantly increased in rosacea, but the role of these TLRs remains unclear in the pathogenesis of rosacea." (PMID 33734592, 2021). "In addition, the fold change of TLR8 and TLR7 ranked as the top two among these TLRs, suggesting that they may take part in the procession of rosacea." (PMID 37780385, 2023). "In order to figure out whether TLR8 and TLR7 act in the etiology of rosacea, we detected the expression of TLR8 or TLR7 in skin samples of participants and conducted a correlation analysis between its mRNA levels and disease severity (including CEA scores and IGA scores) among 24 patients." (PMID 37780385, 2023).
Splenomegaly (4 papers, 2019 to 2023). Abnormal increased size of the spleen. "TLR8 gain-of-function mutations drive splenomegaly, which might be due to macrophage accumulation in the spleen, although monocytosis in peripheral blood is not apparent." (PMID 37462944, 2023). "TLR8−/− deficient mice were hypersensitive to TLR7/8 agonist treatment (R848), showing several indicators of inflammation, such as splenomegaly, increased serum levels of autoantibodies against dsDNA or ribonucleoprotein, and GN." (PMID 32660060, 2020). "To study the role of TLR8 in Slc29a3−/− mice, we generated Slc29a3−/−Tlr8−/− mice, where the phenotypes of splenomegaly and thrombocytopenia were not altered." (PMID 37462944, 2023).
Stroke (4 papers, 2015 to 2025). Sudden impairment of blood flow to a part of the brain due to occlusion or rupture of an artery to the brain. "Then, Tang and colleagues found that TLR8 could promote neuronal apoptosis and T cell-mediated inflammation following stroke." (PMID 32746852, 2020). "Furthermore, we have recently provided evidence that neuronal TLR8 signalling plays a detrimental role by triggering post-stroke inflammation and neuronal cell death." (PMID 25886362, 2015). "Here, we show that the increased expression levels of TLR2, TLR4 and TLR8, adaptor protein MyD88, signalling protein TRAF6, TLR downstream signalling proteins such as NF-κB and MAPKs were significantly prevented in IVIg-treated animals compared to control animals following stroke." (PMID 25886362, 2015). "Unfortunately, there are no studies demonstrating the effects of exosome on TLRs, but the fact that exosome miR-21 was highly expressed in patients with stroke and exosomal miR-21 could activate TLR8 signaling directly a potential negative function of exosome miR-21 in stroke." (PMID 32565722, 2020).
ulcerative colitis (4 papers, 2012 to 2025). An inflammatory bowel disease involving the mucosal surface of the large intestine and rectum. "In fact, patients with ulcerative colitis have higher TLR8 mRNA in colon biopsies than healthy subjects, probably due to bacterial RNA of gut microbiota resulting from microbiota dysbiosis." (PMID 30044791, 2018). "Intestinal inflammation intensity in the ulcerative colitis is positively correlated with TLR8 and inflammatory cytokines such as IL-6 and TNF-α." (PMID 30044791, 2018).
ZIKV infection (4 papers, 2017 to 2024). "Reduced levels of RIG-I and TLR8 mRNA expression have been observed in peripheral blood from patients in the acute phase of ZIKV infection." (PMID 38839691, 2024). "The authors of that study hypothesized that reduced expression of RIG-I and TLR8 during ZIKV infection could be an escape mechanism used by the virus to evade the innate immune response." (PMID 38839691, 2024). "In view of our results showing that other TLRs, such as TLR4, TLR8 and TLR9, are upregulated during ZIKV infection, in particular with the ZIKVAs strain, additional studies are needed to determine the precise involvement of TLR activation in ZIKV pathogenicity." (PMID 31282298, 2019). "Thus, a potential explanation for the inhibition of VDR and CAMP mRNA expression by ZIKV infection could involve the expression of innate immune receptors, such as TLR7 and TLR8, that recognize intracellular viral RNA." (PMID 38839691, 2024). "Although ZIKV infection downregulates TLR7 and TLR8 mRNA expression in human monocytes, we did not observe any effect of VitD3 treatment on TLR7 and TLR8 mRNA expression in either ZIKV-Mon or ZIKV-VitD3-Mon when compared to VitD3-Mon." (PMID 38839691, 2024). "ZIKV infection of engineered or wild-type (WT) cells revealed that the KD of RIG-I, but not TLR7 and TLR8, conspicuously attenuated the ZIKV-induced pyroptotic cell death and GSDME cleavage, suggesting that RIG-I may play a major role in ZIKV-induced pyroptosis." (PMID 35972780, 2022).
acute myeloid leukemia (3 papers, 2020 to 2024). Acute myeloid leukemia (AML) is a group of neoplasms arising from precursor cells committed to the myeloid cell-line differentiation. "Moreover, TLR8 has been shown to induce terminal differentiation-mediated tumor suppression in acute myeloid leukemia (AML)." (PMID 35006413, 2020). "The TLR8 agonist motolimod has been tested against head and neck squamous cell carcinoma in mice and humans, and is showing preclinical efficacy against acute myeloid leukemia (AML)." (PMID 38919608, 2024).
Allergy (3 papers, 2016 to 2020). An allergy is an immune response or reaction to substances that are usually not harmful. "STAT1, STAT3, TLR8, IL13, RFX5 gene polymorphisms have been demonstrated as susceptibility loci for the immune dysregulation in various inflammatory and allergic diseases." (PMID 32886659, 2020). "Targeting TLR8 in allergic disease is facilitated by the availability of potent and selective small molecule (<500 MW) agonists." (PMID 27042301, 2016). "Two TLRs implicated in allergy are TLR7 and TLR8, as studies have found variants in TLR7 and 8 genes contribute to genetic risk for atopic disease." (PMID 27042301, 2016). "However, TLR8 activation using selective agonists as an approach to modify allergic diseases including AR has received little attention." (PMID 27042301, 2016).
atherosclerosis (3 papers, 2014 to 2022). A disease characterized by the build-up of fatty material and calcium deposition in the arterial wall resulting in partial or complete occlusion of the arterial lumen. "Many of the genes differentially regulated during monocyte-to-macrophage differentiation (downregulated genes include JAK2, STAT6, TLR8, and TLR2, and upregulated genes include VEGFB, TGFB1, FN1, IL-1R2, SCARB1, MSR1, and CD163) have been previously reported in the pathogenesis of atherosclerosis." (PMID 25011540, 2014).
cervical cancer (3 papers, 2015 to 2024). A primary or metastatic malignant neoplasm involving the cervix. "The authors demonstrated increased expression of TLR-8 in HeLa cells and in cervical cancer tissue from patients; in this study also was evaluated the correlation between TLR-8 expression and two genes associated to the pathogenesis of cancer like Bcl-2 and VEGF." (PMID 25622528, 2015). "In our study, the expression levels of TLR3, TLR4, TLR7, TLR8, NF-κB p65, and iNOS mRNA in the cervical squamous epithelial cells were significantly higher in the cervical cancer group than in the HR-HPV patients and healthy controls." (PMID 28626766, 2017). "However, in relation to TLR8, previous studies contradict our findings, showing increased expression in cervical cancer samples." (PMID 39208235, 2024). "However, the specific roles of TLR7 and TLR8 in cervical cancer are yet to be elucidated." (PMID 28626766, 2017). "We tested the TLR3, TLR4, TLR7, TLR8, NF-κB p65, and iNOS mRNA expression levels in the cervical tissue epithelial cells of the three groups and found that all mRNA levels were higher in the cervical cancer group than in the HR-HPV group and control group (P < 0.05)." (PMID 28626766, 2017). "However, the relationship between TLR-8 and cervical cancer has been little studied." (PMID 25622528, 2015). "When evaluating the gene expression patterns of TLR transcripts, specifically TLR1, TLR3, TLR4, TLR6, TLR7, TLR8 and TLR10, in HPV+ and HPV- cervical cancer tissue samples, we observed an increase in TLR4 expression and a decrease in TLR1 and TLR3 expression." (PMID 39208235, 2024). "In our study, upregulation of TLR4 in cervical cancer was the most significant among the TLRs examined (including TLR3, TLR4, TLR7, and TLR8)." (PMID 28626766, 2017). "They found a positive correlation between TLR-8 and Bcl2 or VEGF expression both in cervical cancer tissues as well as HeLa cells." (PMID 25622528, 2015). "Recently, it has been reported the involvement of TLR-8 and its relationship with VEGF in cervical cancer." (PMID 25622528, 2015).
Crohn disease (3 papers, 2012 to 2018). A gastrointestinal disorder characterized by chronic inflammation involving all layers of the intestinal wall, noncaseating granulomas affecting the intestinal wall and regional lymph nodes, and transmural fibrosis. "Susceptibility to Crohn's disease (another intestinal inflammatory disease) has also been associated to high TLR8 levels." (PMID 30044791, 2018).
gastric cancer (3 papers, 2017 to 2021). A primary or metastatic malignant neoplasm involving the stomach. "We found that immune related genes such as TLR8, Interleukin-7 (IL-7), Leptin (LEP), IL1RN had intimate relationships with AQP9 expression in breast, colon, lung and gastric cancers." (PMID 33247170, 2020). "Overlap analysis with genes that co-expressing in 381 gastric cancer tissues and 37 gastric cells demonstrates that various immune related genes such as CCL18, TLR8, C3AR1, CYSLTR2 and CD86 are positively correlated with CD163." (PMID 29152078, 2017). "Researchers found that Scutellaria baicalensis Georgi can regulate the expression of TLR8, HIF-1α, PDGFβ, and PTEN in gastric cancer cells, which can inhibit invasion, migration, and epithelial-mesenchymal transition of gastric cancer cells through NF-κB/Snail signaling pathway." (PMID 34421596, 2021).
lung adenocarcinoma (3 papers, 2024 to 2026). A carcinoma that arises from the lung and is characterized by the presence of malignant glandular epithelial cells. "Bioinformatics analysis revealed that downregulation of TLR4 and TLR8 positively impacts the survival in lung adenocarcinoma (LUAD) and lung squamous cell carcinoma (LUSC)." (PMID 40025339, 2025). "Therefore, we hypothesized that melittin‐MIL‐2 suppressed the proliferation of human lung adenocarcinoma cell A549 by downregulating the expression of TLR8 and VEGF, thereby playing a role in inducing cell apoptosis." (PMID 39003635, 2024). "Here, levels of TLR‐8 and VEGF were declined in A549 lung adenocarcinoma cells exposed to melittin‐MIL‐2 in vitro." (PMID 39003635, 2024).
metabolic syndrome (3 papers, 2016 to 2025). A cluster of metabolic risk factors for CARDIOVASCULAR DISEASES and TYPE 2 DIABETES MELLITUS. "Here, we report the implication of TLR7 signaling in high fat diet (HFD)-induced metabolic syndrome and exacerbation of lupus autoimmunity in TLR8-deficient (TLR8ko) mice, which develop spontaneous lupus-like disease due to increased TLR7 signaling by dendritic cells (DCs)." (PMID 31552019, 2019). "Thus, in the current study we evaluated the impact of high fat diet (HFD) on the development of SLE and metabolic syndrome in TLR8-deficient mice (TLR8ko) that spontaneously develop SLE due to increased TLR7 signaling by DCs." (PMID 31552019, 2019). "However, the altered TLR8 expression did not associate with corpulence phenotypes in T2D individuals that happen to be more heterogeneous due to presence of dyslipidemia and related complications." (PMID 27980459, 2016).
multiple sclerosis (3 papers, 2013 to 2017). A progressive autoimmune disorder affecting the central nervous system resulting in demyelination. "The balance of TLR8 signaling is critical to the maintenance of homeostasis, as the lack or impairment of TLR8 signaling is detrimental in some diseases such as multiple sclerosis." (PMID 29416532, 2017). "Our findings also point to a destructive role of TLR8 in EAE and shed lights on pathogenesis of multiple sclerosis." (PMID 23516559, 2013).
myeloma (3 papers, 2013 to 2017). "Analysis of toll-like receptor (TLR) expression at protein level indicated that TLR1, TLR3, TLR4, TLR7, TLR8, and TLR9, were similarly expressed in most human myeloma cell lines, including L363 and RPMI 8226 cells, as well as in primary cells from MM patients." (PMID 28702457, 2017). "Other inflammatory cytokines known to support myeloma growth, such IL6 and CCL3 were also secreted into the supernatant after stimulation of the bone marrow monocytes with the TLR8 agonist." (PMID 26029369, 2015). "Expression of mRNA for TLR1, TLR3, TLR4, TLR5, TLR7, TLR8, and TLR9 was found in all myeloma cell, but levels of mRNA expression differed amongst different cell lines." (PMID 23593278, 2013).
neuroblastoma (3 papers, 2017 to 2021). Neuroblastoma (NB) is the most common solid, extracranial childhood tumor. "EV-miR-21 from neuroblastoma cells is transferred to monocytes, which can differentiate into macrophages, and upregulates miR-155 expression by binding TLR8; the educated monocytes in turn secrete EV-miR-155 to induce chemotherapy resistance by targeting TERF1 in neuroblastoma cells." (PMID 32503543, 2020).
periodontitis (3 papers, 2019 to 2023). An acute or chronic inflammatory process that affects the tissues that surround and support the teeth. "It has been shown that the cellular expression of all TLRs (apart from TLR7 and TLR8) differs significantly between healthy controls and periodontitis patients, implying a contribution in periodontitis’ pathogenesis." (PMID 31817424, 2019). "In a study on HIV-positive North American patients with periodontitis, 8 SNPs in 6 TLR genes (TLR1 (n = 2), TLR2 (n = 1), TLR4 (n = 1), TLR6 (n = 1), TLR8 (n = 2), and TLR9 (n = 1)) were positively associated with P. gingivalis (2 SNPs), T. denticola (6 SNPs), and T. forsythia (1 SNP)." (PMID 35122548, 2022).
aspergillosis (2 papers, 2020 to 2023). Aspergillosis is an infection, growth, or allergic response caused by the Aspergillus fungus. "In recent years, the role of intracellular pattern recognition receptors (TLR3, TLR7, TLR8, and TLR9) has become increasingly important in the pathophysiology of some mycoses, such as paracoccidioidomycosis, cryptococcosis, aspergillosis, and candidiasis." (PMID 37233274, 2023). "In recent years, the role of intracellular pattern recognition receptors (TLR3, TLR7, TLR8, and TLR9) has become increasingly important in the pathophysiology of some mycoses, as paracoccidioidomycosis, cryptococcosis, aspergillosis, and candidiasis." (PMID 33194839, 2020).
autoimmune glomerulonephritis (2 papers, 2012 to 2014). An autoimmune form of glomerulonephritis (disease). "Demaria and colleagues reported that Tlr8−/− mice develop autoimmune glomerulonephritis due to excessive TLR7 expression and activation, and that this was attenuated in double Tlr7−/−/Tlr8−/− mice." (PMID 22848646, 2012).
autoimmune hemolytic anemia (2 papers, 2022 to 2023). Autoimmune hemolytic anemia (AIHA) is an autoimmune disorder in which various types of auto-antibodies are directed against red blood cells causing their survival to be shortened and resulting in hemolytic anemia. "Another study identified a missense TLR8 mutation leading to partial TLR8 deficiency in monozygotic twin boys with severe autoimmune hemolytic anemia and a TLR7-dependent autoinflammatory phenotype." (PMID 37723501, 2023). "A case study revealed that a germline missense mutation (G572V) in the TLR8 gene in identical male twins, led to reduced TLR8 protein levels in monocytes and granulocytes and increased TLR7 signaling, which caused severe autoimmune hemolytic anemia and autoinflammation." (PMID 36389822, 2022).
bladder cancer (2 papers, 2021 to 2023). "These early studies around clinical samples of bladder cancer verified the potential poor prognosis of TLR8 in bladder cancer." (PMID 38063246, 2023). "The expression of TLR8 in high‐grade (Hg) bladder cancer was higher than that in low‐grade (LG) bladder cancer." (PMID 38063246, 2023). "TLR8+CK+ cells (2.68%) and TLR8+PD‐L1+ cells (0.51%) were also found in bladder cancer tissues." (PMID 38063246, 2023).
breast tumor (2 papers, 2019 to 2021). "breast tumor myeloid cells, the expression of 5 TLR genes (TLR1, TLR2, TLR4, TLR7 and TLR8) were detected in >10% of cells and at moderate to high expression levels." (PMID 34956864, 2021). "Transcriptional analysis showed preferential expression of TLR8 and TLR7 in the LNR-cDC and –pDC subsets respectively (as opposed to migratory DC), both in HLN and BrC SLN, which were the exact DC subsets we identified as affected in the breast tumor-draining SLN." (PMID 31118093, 2019).
Cerebral ischemia (2 papers, 2015 to 2021). Restriction of arterial blood supply to the brain associated with insufficient oxygenation to support the metabolic requirements of the tissue. "Studies have shown that TLR8 expression was significantly increased at 6 h after cerebral ischemia in mice, and in in vitro oxygen-glucose deprivation (OGD) in cells, the expression levels of TLR8 and the downstream JNK signaling pathway were also significantly upregulated." (PMID 25928750, 2015).
co-infection (2 papers, 2020 to 2022). "Most TLR mRNAs, including TLR4, TLR5, and TLR8 were upregulated in the severe group, consistent with viral and bacterial co‐infection that was common among severe cases." (PMID 33135345, 2020). "The earlier up-regulatory effect of PEDV/PDCoV co-infection in the expression levels of TLR7, TLR8, and TLR9, as compared with the single-infection groups, support our hypothesis concerning the potential synergistic effect." (PMID 36376395, 2022). "Interestingly, PDCoV/PEDV co-infection showed a transient up-regulatory effect on TLR7, TLR8, and TLR9 by 3 DPI." (PMID 36376395, 2022).
cutaneous T cell lymphoma (2 papers, 2022 to 2025). "Resiquimod, also known as R848, is a small molecule agonist of both TLR7 and TLR8 that has been evaluated using a topical formulation in clinical trials for the treatment of cutaneous T cell lymphoma (CTCL)." (PMID 36123697, 2022).
Dengue (2 papers, 2020 to 2023). "TLR7 and TLR8 are capable of recognizing single-stranded RNA, which is another form of viral RNA produced during the dengue virus infection." (PMID 37631896, 2023). "In summary, Toll-like receptors such as TLR3, TLR7, and TLR8 play significant roles in the innate immune response against dengue virus infection." (PMID 37631896, 2023).
dilated cardiomyopathy (2 papers, 2020 to 2024). Cardiomyopathy which is characterized by dilation and contractile dysfunction of the left and right ventricles. "Accumulating evidence demonstrates the important role of TLR signaling in the development of cardiovascular disease, whereas Tlr8 transcripts increased in patients with enterovirus-induced dilated cardiomyopathy." (PMID 39202335, 2024).
endometriosis (2 papers, 2020 to 2025). The growth of functional endometrial tissue in anatomic sites outside the uterine body. "We observed markedly higher expression of TLR2, TLR3, TLR4, TLR7, TLR8, and TLR9 on CD4+, CD8+, and CD19+ lymphocytes in the endometriosis group, indicating their active participation in modulating immune responses in the disease setting." (PMID 40862752, 2025).